MAG (myelin associated glycoprotein)
Diseases named in the same sentence as MAG in open-access papers (continued):
Sharing a sentence is not in itself a finding about the gene and the disease.
glioma (6 papers, 2008 to 2023). A benign or malignant brain and spinal cord tumor that arises from glial cells (astrocytes, oligodendrocytes, ependymal cells). "The volcano plot revealed that glial cells in C5 derived from TDL upregulated expression of myelin-related genes (TYMP, CD9, MAG, and PMP22) and immune-related and inflammatory response-associated genes (IL1B and CXCL8) comparing to those from glioma." (PMID 36085357, 2022). "Because isocitrate dehydrogenase (IDH) glioma mutants showed a better prognosis compared to IDH-wildtype glioma patients, in the astrocytic brain tumour subgroup we also analyzed Nogo-A, MAG, and OMgp levels depending on the IDH1 gene mutation." (PMID 34601991, 2021). "After the injury, such as those occurring during glioma invasion, Nogo-A, MAG, and OMgp are released from the cell membrane to the extracellular space." (PMID 34601991, 2021). "A previous study showed that Nogo-66 and MAG inhibit the adhesion and migration of NgR-expressing glioma cells." (PMID 31649250, 2019). "Meanwhile, the expressions of myelin-associated proteins (MBP, MOG, MAG and CNP) were unanimously reduced in gliomas." (PMID 30034322, 2018). "The extracellular pool of Nogo-A and MAG could be of principal importance for glioma growth as NgR1 activation by these proteins inhibits glioma cell motility and invasiveness in vitro." (PMID 34601991, 2021). "In IDH-mutant/PM gliomas, coordinated hypermethylation in the transcription start site (TSS)/CpG island regions was observed in MO marker (GALC/O1), myelin components (MAG, MBP, MOBP, MOG), and essential regulators of the myelination program (MYRF/C11orf9 and SOX10)." (PMID 37055795, 2023). "This sequence has not been identified in previous studies related to the MAG gene promoter, probably due to the differences in experimental conditions (we used Schwann cell primary culture instead of the C6 glioma cell line, which has been used in other studies)." (PMID 18941509, 2008).
pancreatic cancer (6 papers, 2010 to 2025). "MUC1, found on pancreatic cancer cells, interacts with Myelin-associated glycoprotein (MAG) on Schwann cells, enhancing cancer cell survival within nerves." (PMID 40696378, 2025). "STn and Tn on MUC1 expressed on tumor cells contribute to perineural invasion in pancreatic cancer by binding to myelin-associated glycoprotein (MAG), a member of the Siglec family of sialic acid-binding lectins expressed on oligodendrocytes and Schwann cells." (PMID 24212946, 2011). "MUC1 binding to Siglec-4a (myelin associated glycoprotein) contributes to perineural adhesion of pancreatic cancer cells." (PMID 20497550, 2010). "During PNI in pancreatic cancer, cancer cells that overexpress membrane-bound mucin 1 (MUC1) can establish strong adhesion with myelin-associated glycoprotein (MAG) on Schwann cells." (PMID 39061654, 2024).
Waldenström macroglobulinemia (6 papers, 2013 to 2025). "Moreover, in anti-MAG patients, hematological follow-up is required due to the progression risk of M-component to hematological malignancies, such as multiple myeloma, Waldenstrom macroglobulinemia, amyloid light-chain (AL) amyloidosis, with an approximate risk of 1% per year." (PMID 36672019, 2022).
autoimmune disease (5 papers, 2012 to 2024). A disorder resulting from loss of function or tissue destruction of an organ or multiple organs, arising from humoral or cellular immune responses of the individual to their own tissue constituents. "Because myelin-associated glycoprotein-related neuropathy and psoriatic arthritis are both considered autoimmune diseases, we conclude that intravenous immunoglobulin therapy is very effective for patients with an association of these diseases." (PMID 23286283, 2013). "Rheumatoid factor and serum Anti-GM1, Anti-MAG, and Anti-Hu antibodies excluded neuronal-specific autoimmune diseases." (PMID 39766823, 2024). "Circulating anti-MAG antibodies may play an etiopathogenic role in some autoimmune disorders as autoimmune chronic demyelinating neuropathy." (PMID 22898564, 2012). "Moreover, demyelination in the context of autoimmune diseases due to antibodies produced against MOG and MAG has been identified." (PMID 35652161, 2022).
dementia (5 papers, 2014 to 2023). Loss of intellectual abilities interfering with an individual's social and occupational functions. "While we detected similar levels of MAG protein in men and women with dementia, suggesting a comparable extent of ischemic injury in both genders based on MAG/PLP ratio, the severity of WM pathology observed in women was greater than that observed in men." (PMID 26983404, 2016). "Using this approach in our dementia samples, we observed that MAG/PLP ratio was significantly lower in females (0.2) than in males (0.5), indicating greater severity of WM pathology in women with AD + CVD." (PMID 26983404, 2016). "VEGF concentration correlated negatively with the MAG:PLP1 ratio in both the South West Dementia Brain Bank cohort (r = −0.315, P = 0.0015) and the Oxford cohort (r = −0.631, P < 0.0001)." (PMID 24618270, 2014).
demyelinating polyneuropathy (5 papers, 2015 to 2024). Polyneuropathy that is characterized by demyelination of axons. "This case report contributes to the limited but growing evidence on the association of anti-MAG-associated demyelinating peripheral neuropathy with chronic respiratory failure." (PMID 38912071, 2024). "Serum protein electrophoresis and immunofixation identified an IgM kappa monoclonal protein and further testing confirmed high titers of anti-myelin-associated glycoprotein (MAG) antibodies, leading to a diagnosis of anti-MAG-associated demyelinating peripheral neuropathy." (PMID 38912071, 2024). "In this series, the ELISA test with a cut-off value of 1500 BTU was proven more sensitive than WB (71.2% versus 54%) to detect anti-MAG antibodies in patients with IgM MG and a demyelinating polyneuropathy." (PMID 26065001, 2015). "The pathophysiology linking anti-MAG-associated demyelinating peripheral neuropathy with respiratory failure is not currently well understood." (PMID 38912071, 2024). "Monoclonal gammopathies of neurological significance include a widespread range of manifestations, ranging from slowly progressive sensitive demyelinating polyneuropathy with anti-MAG antibody to subacute rapidly progressive forms as in POEMS syndrome or neurolymphomatosis." (PMID 35326711, 2022). "The pathophysiology of this condition is likely to involve anti-MAG antibody deposition on myelin sheaths of the peripheral nerves and it is supposed to be distinct from chronic inflammatory demyelinating neuropathy (CIDP), another immune-mediated demyelinating peripheral neuropathy." (PMID 26065001, 2015).
demyelination (5 papers, 2017 to 2025). "Experimental studies demonstrated that mice immunized with casein developed demyelination associated with cross-reactivity toward myelin-associated glycoprotein (MAG), a key protein involved in myelin adhesion and stability." (PMID 41228487, 2025). "WML in the control cases, that primarily consisted of demyelination, were found to be the result of ischemia as indicated by a significant reduction in the MAG:PLP ratio." (PMID 28638989, 2017). "These higher expressions of MAG, MBP, and CDK5 in TG mice increase protecting adaption, thus decrease the sensitivity to METH-induced demyelination." (PMID 29467717, 2018).
Nystagmus (4 papers, 2017 to 2024). Rhythmic, involuntary oscillations of one or both eyes related to abnormality in fixation, conjugate gaze, or vestibular mechanisms. "Moreover, MAG deficiency has been associated with the occurrence of a nystagmus in myelin-associated diseases." (PMID 28851966, 2017). "It was recently published that AHR-KO are afflicted by a nystagmus and found to have an impaired optic nerve myelin sheath along with modifications in lipid composition and in the expression of MAG." (PMID 33193710, 2020). "In order to identify the signaling pathways involved in all observed phenomenon at the functional, cellular and molecular levels (nystagmus, demyelination, MAG expression), we investigated the transcriptomes of the AhR-KO and WT optic nerves." (PMID 28851966, 2017).
Paraproteinemia (4 papers, 2021 to 2022). An abnormal immunoglobulin or part of an Ig (light chain) in the circulation. "Anti-myelin-associated glycoprotein (MAG) IgM paraprotein-related peripheral neuropathy (anti-MAG PN) is the most prevalent variant of the immunoglobulin M (IgM) paraproteinemia-related peripheral neuropathies (PN) accounting for approximately 50% of cases." (PMID 35157138, 2022). "In this prospective cohort study, we included 24 treatment-naïve patients with anti-MAG PN (mean age 69 years, 57% male) that had IgM paraproteinemia, a high IgM MAG-antibody, and clinical diagnosis of anti-MAG PN by a neurologist specialized in peripheral nerve disorders." (PMID 35157138, 2022). "DADS without monoclonal paraproteinemia or anti-MAG antibody, also referred to as DADS-I, is considered as a variant of CIDP." (PMID 33790853, 2021).
Oculomotor apraxia (3 papers, 2020 to 2024). Ocular motor apraxia is a deficiency in voluntary, horizontal, lateral, fast eye movements (saccades) with retention of slow pursuit movements. "Oculomotor apraxia is here described for the first time in association with MAG variants, broadening its clinical phenotype." (PMID 32340215, 2020).
autoimmune neuropathies (2 papers, 2020 to 2022). "Rituximab, a chimeric monoclonal antibody against CD20 + B lymphocytes, is currently the most used, especially in anti-MAG antibody neuropathy and autoimmune neuropathies with antibodies to nodal/paranodal antigens that are unresponsive to IVIg." (PMID 35349079, 2022).
Autoimmunity (2 papers, 2012 to 2016). The occurrence of an immune reaction against the organism's own cells or tissues. "This study was the first to investigate the relationship between serum levels of 25-hydroxy vitamin D and anti-MAG auto-antibodies, as indicators of autoimmunity to brain tissue, in a group of autistic children." (PMID 22898564, 2012).
brain tumour (2 papers, 2021 to 2024). "The obtained results indicated CSF Nogo-A and serum MAG evaluation as potential circulating diagnostic markers of primary brain tumours." (PMID 34601991, 2021). "In the next step, we compared the diagnostic utility of evaluating the three myelin-associated proteins of interest (Nogo-A, MAG, OMgp) in patients with primary brain tumour." (PMID 34601991, 2021). "Taking into account the possibility of myelin-associated proteins having a role in brain tumour development, the study aimed to evaluate the diagnostic usefulness of myelin-associated proteins (Nogo-A, MAG, OMgp) released into extracellular space in patients with brain tumours." (PMID 34601991, 2021). "Taking into account the possibility of myelin-associated proteins having a role in brain tumour development, the study aimed to evaluate whether CSF and serum MAG and OMgp concentrations are different between astrocytic and meningeal tumour patients compared to non-tumoural individuals." (PMID 34601991, 2021). "Our results indicated the potential usefulness of CSF Nogo-A and serum MAG evaluation as circulating biomarkers of primary brain tumours." (PMID 34601991, 2021). "The diagnostic utility analysis indicated the usefulness of CSF Nogo-A and serum MAG concentration evaluation to confirm primary brain tumour diagnosis." (PMID 34601991, 2021). "Our study is the first which evaluated MAG and OMgp concentrations in CSF and serum of patients with primary brain tumours." (PMID 34601991, 2021). "Although the involvement of Nogo-A, MAG, and OMgp in the inhibition of central nervous system regeneration has been widely studied, the data on their role in brain tumour pathophysiology is scarce." (PMID 34601991, 2021). "Patients with brain tumour had significantly higher median CSF MAG concentrations compared to serum MAG values (7.43 ng/mL vs. 0.00 ng/mL; p < .001)." (PMID 34601991, 2021). "In the next step, we conducted ROC analysis to investigate the accuracy of CSF Nogo-A and serum MAG concentration evaluation to differentiate patients with primary brain tumour (astrocytic brain tumours plus meningeal brain tumours) from non-tumoural individuals." (PMID 34601991, 2021). "To find out whether the concentrations of Nogo-A, MAG, and OMgp may predict brain tumour diagnosis, we conducted logistic regression analysis." (PMID 34601991, 2021). "Nogo-A, MAG, and OMgp concentrations in patients with brain tumours compared to non-tumoural individuals." (PMID 34601991, 2021). "We found that serum MAG concentration in patients with primary brain tumour was significantly lower compared to non-tumoural individuals." (PMID 34601991, 2021). "We showed that both serum MAG and serum OMgp concentrations in the combined brain tumour groups were statistically lower compared to the non-tumoural group." (PMID 34601991, 2021). "The combined brain tumour groups had statistically lower serum MAG concentrations compared to the non-tumoural group (p = .004)." (PMID 34601991, 2021). "Overall, the group of patients with brain tumour had lower CSF MAG concentrations compared to the non-tumoural group, but it was not significant (p = .508)." (PMID 34601991, 2021). "Thus, we suggest that MAG expression within myelin of the peripheral nervous system in patients with primary brain tumour may be lower compared to non-tumoural individuals." (PMID 34601991, 2021).
breast carcinoma (2 papers, 2012 to 2023). "They found that MAG-Tn3 induced Tn-specific antibodies that killed Tn-positive cancer cells of human and MAG-Tn3 was now being evaluated for cancer vaccine in breast cancer patients (phase I clinical trial)." (PMID 36794282, 2023). "Furthermore, breast cancers may metastasize to the brain where the MAG is abundantly expressed." (PMID 22453032, 2012).
cerebrovascular disease (2 papers, 2019 to 2023). "Myelin-associated glycoprotein and proteolipid protein 1 correlated with the ischaemic injury scale score, a global indicator of cerebrovascular disease (r = −0.23 and −0.20, respectively, Ps < 0.01)." (PMID 36895961, 2023). "Results showed that lower MAG and PLP were associated with cerebrovascular disease pathologies." (PMID 36895961, 2023).
experimental autoimmune encephalomyelitis (2 papers, 2023). An autoimmune demyelinating disease of the central nervous system that is produced experimentally in animals by the injection of homogenized brain or spinal cord in Freund's adjuvant. "Genetic deletion of MAG in animal models resulted in accelerated axonal loss in experimental autoimmune encephalomyelitis (model of MS), supporting the notion that MAG plays a role in protecting axons in disease conditions." (PMID 38137554, 2023).
fucosidosis (2 papers, 2015 to 2023). "A detailed examination of OL status in a canine model of fucosidosis identified significant OL loss in the corpus callosum and cerebellar white matter, which stabilized by 16 weeks of age, as visualized by decreased CNP, MAG, MAL and PLP1 expression, and reduced CNP and increased CASP6 staining." (PMID 37183607, 2023).
hereditary spastic paraplegia (2 papers, 2020). Hereditary spastic paraplegias (HSP) comprise a genetically and clinically heterogeneous group of neurodegenerative disorders characterized by progressive spasticity and hyperreflexia of the lower limbs. "Homozygous variants in MAG, encoding myelin-associated glycoprotein (MAG), have been associated with complicated forms of hereditary spastic paraplegia (HSP)." (PMID 32340215, 2020).
hypomyelinating leukodystrophies (2 papers, 2016 to 2020). "Broadly, the characterization of the extremely short yet oligodendrocyte-specific human MAG promoter may facilitate modeling neurological diseases caused by oligodendrocyte pathology and has translational relevance for leukodystrophy gene therapy." (PMID 26941604, 2016). "Mutations affecting genes that encode classical myelin proteins including PLP, CNP, MAG, TUBB4, and ASPA cause severe neurological disorders including hypomyelinating leukodystrophies (HLD) and spastic paraplegias (SPG)." (PMID 32973451, 2020).
ischemia (2 papers, 2014 to 2017). A hypoperfusion of the BLOOD through an organ or tissue caused by a PATHOLOGIC CONSTRICTION or obstruction of its BLOOD VESSELS, or an absence of BLOOD CIRCULATION. "In a study of two independent post-mortem cohorts, we recently showed that the ratio of myelin-associated glycoprotein (MAG) to proteolipid protein 1 (PLP1) in the white matter correlated inversely with the severity of small vessel disease, and so presumably with the degree of ante-mortem ischemia." (PMID 25309424, 2014).
melanoma (2 papers, 2022 to 2024). A malignant, usually aggressive tumor composed of atypical, neoplastic melanocytes. "Both melanoma-activated SCs with high MAG expression and recombinant MAG independently increased the immunosuppressive activity of MDSCs in T-cell inhibitory assay." (PMID 39769484, 2024).
optic neuritis (2 papers, 2005 to 2024). Optic neuritis is inflammation of the optic nerve, the nerve that carries the visual signal from the eye to the brain.The conditionmay cause sudden, reduced vision in the affected eye(s). "In another study, transgenic mice with T-cell receptors specific to myelin associated glycoprotein (MAG) spontaneously presented with optic neuritis." (PMID 16168081, 2005).
progressive multifocal leukoencephalopathy (2 papers, 2013 to 2023). Progressive multifocal leukoencephalopathy (PML) is a neurological disorder that damages the myelin that covers and protects nerves in the white matter of the brain. "DO type demyelination with preferential MAG loss has been reported in various demyelinating conditions, such as acute MS, NMOSD, Baló's concentric sclerosis, and progressive multifocal leukoencephalopathy." (PMID 36368713, 2023). "Preferential MAG loss is thought to be an early neuropathological sign of oligodendrocyte dysfunction and has been reported in different conditions, including acute MS, Baló-like lesions, progressive multifocal leukoencephalopathy (PML) and acute hypoxic conditions." (PMID 23991165, 2013).
Sensorimotor neuropathy (2 papers, 2015 to 2022). "Nearly all anti-MAG PN patients (96%) presented with the classic phenotype of a chronic and slowly progressive sensorimotor neuropathy with the exception of one patient who presented with a subacute phenotype with rapid progression." (PMID 35157138, 2022).
acquired von Willebrand disease (1 paper, 2013). "Neuropathies, which are caused in part by immunoreactivity of IgM to myelin-associated glycoprotein (MAG), IgM-mediated glomerulonephritis, angioedema, and acquired von Willebrand disease have all been reported." (PMID 24106612, 2013).
acute porphyrias (1 paper, 2025). "Antibodies against myelin-associated glycoprotein (Anti-MAG) and ganglioside antibodies tested negative, as did the laboratory markers for acute porphyrias." (PMID 39801702, 2025).
Alexander disease (1 paper, 2020). Alexander disease (AxD) is a rare neurodegenerative disorder of the astrocytes comprised of two clinical forms: AxD Type I and Type II manifesting with various degrees of macrocephaly, spasticity, ataxia and seizures and leading to psychomotor regression and death. "Interestingly, some RNAs including PLP1 (SPG2), MAG (SPG75), and GFAP (Alexander disease) are expressed in none of the cell types studied here." (PMID 33072739, 2020).